TUBGCP6 (tubulin gamma complex component 6)
Description:
Component of the gamma-tubulin ring complex (gTuRC) which mediates microtubule nucleation. The gTuRC regulates the minus-end nucleation of alpha-beta tubulin heterodimers that grow into microtubule protafilaments, a critical step in centrosome duplication and spindle formation.
Synonyms: GCP-6; GCP6; KIAA1669; DJ402G11.6; MCCRP; MCCRP1; MCPHCR
Tractability: Small molecule: a structure with a bound ligand is known. PROTAC: ubiquitination databases record sites on it; its protein half-life has been measured.
Gene: Protein-coding gene on chromosome 22 (50,217,688 to 50,245,028, reverse strand). Ensembl gene ENSG00000128159.
Subcellular location: Cytoplasm, cytoskeleton, microtubule organizing center, centrosome
Pathways (Reactome):
Cell Cycle: Recruitment of NuMA to mitotic centrosomes; Recruitment of mitotic centrosome proteins and complexes
Gene Ontology:
Molecular function: microtubule binding; gamma-tubulin binding; microtubule minus-end binding
Biological process: microtubule nucleation; meiotic cell cycle; mitotic cell cycle; spindle assembly; microtubule cytoskeleton organization
Cellular component: centrosome; gamma-tubulin ring complex; membrane; cytosol; gamma-tubulin complex; microtubule organizing center; spindle pole
Genetic constraint (gnomAD): Loss-of-function variants: 161 observed, 171.4 expected, observed/expected ratio (o/e) 0.94, 90% interval 0.82 to 1.07. The synonymous counts are far from expectation, so gnomAD's model fits this gene poorly and the ratio says little. Missense variants: 2,572 observed, 2,435.1 expected, observed/expected ratio (o/e) 1.06, 90% interval 1.02 to 1.09. Synonymous variants: 1,173 observed, 1,014.6 expected, observed/expected ratio (o/e) 1.16, 90% interval 1.1 to 1.21.
Gene-disease validity (ClinGen):
ClinGen rates the evidence that TUBGCP6 causes each of these diseases.
microcephaly and chorioretinopathy 1 (autosomal recessive): Definitive. An autosomal recessive disorder caused by mutation(s) in the TUBGCP6 gene, encoding gamma-tubulin complex component 6.
Homologues: Orthologues: macaque TUBGCP6 (90% identical), rat Tubgcp6 (75% identical), mouse Tubgcp6 (75% identical), guinea pig TUBGCP6 (71% identical), dog TUBGCP6 (71% identical), pig TUBGCP6 (71% identical), chimpanzee TUBGCP6 (71% identical), tropical clawed frog tubgcp6 (53% identical), zebrafish appl2 (38% identical), Drosophila melanogaster Grip163 (16% identical). Paralogues in human: TUBGCP5 (13% identical), TUBGCP3 (11% identical), TUBGCP2 (10% identical), TUBGCP4 (8% identical).
Diseases named in the same sentence as TUBGCP6 in open-access papers:
TUBGCP6 is named in the same sentence as 18 diseases in open-access papers, as found by Europe PMC text mining. Sharing a sentence is not in itself a finding about the gene and the disease. The quoted sentences say what the papers report.
microcephaly (5 papers, 2012 to 2025). A congenital or acquired developmental disorder in which the circumference of the head is smaller than normal for the person's age and sex. "Gamma-complex component genes (TUBGCP4, TUBGCP5, and TUBGCP6) are critical in neuronal progenitor proliferation, and its variants cause cell proliferation defects and increased apoptosis, which have been reported to be associated with microcephaly." (PMID 40017707, 2025). "We predict that defects in TUBGCP6, CDK5RAP2 and CENPJ cause primary microcephaly by similar mechanisms." (PMID 22279524, 2012). "Autosomal recessive forms of microcephaly with chorioretinopathy are caused by mutations of the genes of the master regulator of centriole duplication, the PLK4 kinase (MCCRP2, MIM 616171), and their substrates TUBGCP4 (MCCRP3, MIM 616335) and TUBGCP6 (MCCRP1, MIM 251270)." (PMID 27099632, 2016).
anaplastic large cell lymphoma (1 paper, 2018). Anaplastic large cell lymphoma (ALCL) is a rare and aggressive peripheral T-cell non-Hodgkin lymphoma, belonging to the group of CD30-positive lymphoproliferative disorders, which affects lymph nodes and extranodal sites. "Interestingly, TUBGCP6, the human orthologue of Alp16, is commonly mutated or amplified in anaplastic large cell lymphoma (ALCL)." (PMID 29720420, 2018).
developmental delay (1 paper, 2021). "Significant developmental delay in this individual could be a result of TUBGCP6 deletion." (PMID 34228749, 2021).
hearing loss (1 paper, 2017). "Apart from a heterozygous frameshift mutation in TUBGCP6, c.5001_5003delinsCA (p.Gln1667Hisfs*11), NGS of the known genes for Usher syndrome, for other syndromic and isolated hearing loss, and for retinal degeneration did not identify any mutations." (PMID 28469144, 2017).
melanoma (1 paper, 2024). A malignant, usually aggressive tumor composed of atypical, neoplastic melanocytes. "Among the 26 shared mutated genes in melanoma B16-F1GFP-D and B16-FGFP-M cells, two genes (Ddx18 and Tubgcp6) were amplified in both parental and dormant cells." (PMID 39223638, 2024).
neuropathies (1 paper, 2020). "At least TUBGCP6, SYNE1, BPTF, KIDINS220, MYO5A, VPS13B, TBC1D24) are known to contain mutations causing various neuropathies." (PMID 32561887, 2020).
viral infection (1 paper, 2025). "TUBGCP6 contributes to microtubule nucleation and centrosome integrity—structures frequently remodeled during viral infection." (PMID 41366310, 2025).
TUBGCP6 also shares sentences with these, for which no sentence is quoted: breast carcinoma (1 paper); cancer (1); glioblastoma (1); Lissencephaly (1); Macrogyria (1); Primary microcephaly (1); primordial dwarfism (1); retinal degeneration (1); seminoma (1); tumor (1); Usher syndrome (1).